CD276 (CD276 molecule)
Diseases named in the same sentence as CD276 in open-access papers (continued):
Sharing a sentence is not in itself a finding about the gene and the disease.
cancer (continued). "In two meta-analyses, increased expression of CD276 in many types of malignant tumors was associated with poor OS (HR = 2.09, 95% CI = 1.60–2.74, p < 0.001; HR = 1.58, 95% CI = 1.32–1.90, p < 0.00001, respectively)." (PMID 34943606, 2021). "B7-H3 (also known as CD276) is also a targetable T-cell inhibitory receptor that is associated with poor clinical outcomes of cancers." (PMID 34064396, 2021). "CD276, known as B7-H3, belongs to the B7 family of immunoregulatory proteins and has been implicated in cancer progression and metastasis." (PMID 33869027, 2021). "Accumulating evidence shows that CD276 is involved in biological processes underlying cancer development, including proliferation, migration, invasion, drug resistance, and metabolism." (PMID 34680929, 2021). "MIR100HG was significantly correlated with the expression of CD200, CD274 and CD276 in pan‐cancers and was significantly associated with the abundance of central memory CD8 T cells, effector memory CD4 T cells and effector memory CD8 T cells in pan‐cancers." (PMID 33797188, 2021). "Our study showed a strong association of CD200 and CD276 expression with cancer stem cells, which implies unique immune features of cancer stem cells and increases the possibility of utilizing immunotherapy to eliminate them." (PMID 33932112, 2021). "Studies have shown that CD276 helps to suppress normal immune responses and can cause cancer progression in patients with NSCLC." (PMID 31737785, 2019). "CD276 is a NB-associated molecule that protects cancer cells from the attack of natural-killer cells." (PMID 24069378, 2013). "In addition, CD276, the gene encoding B7 homolog 3 (B7-H3), an inhibitory ligand overexpressed in certain cancers, was elevated in the high-risk group." (PMID 41139700, 2026). "It indicated that the immune function caused by CD276 mAb-Exo-AAC could offer additional therapeutic benefits in targeted cancer treatment." (PMID 41462289, 2025). "Besides, we also found that only CD276 was positively associated with UBA1 in most cancers, however, there are many other immune checkpoints like CD44, CD86 and CD274 illustrating a positive correlation with UBA6." (PMID 40046044, 2025). "Matrix metalloproteinase inhibitors caused an increase of cell-surface CD276 expression in cancer cells and a decrease in soluble CD276 levels in the supernatant 13, indicating that soluble CD276 is produced by the cleavage of cell-surface CD276 via the effect of matrix metalloproteinase." (PMID 38902359, 2024). "Here, we assess the clinicogenomic features associated with B7-H3 (CD276) expression to delineate which cancers may benefit the most from B7-H3 targeted therapies." (PMID 38709075, 2024). "This identification of CD276 as a cancer-associated cell surface antigen in both ESCC and other solid tumors suggests that it could function as a useful CAR targeting marker for engineering NK therapy." (PMID 38566988, 2024). "The antitumor effect of CD276 blockade is comprehensive, including the activation of T cell response, polarization of TAMs, induction of dendritic cells function, and inhibition of cancer-associated fibroblasts (CAF) activation." (PMID 38561369, 2024). "The co-localization of CD147 and CD276 in LRMs, their impact on cancer stemness, and their association with unfavorable clinical outcomes and chemotherapeutic resistance in HER2+ BC and TNBC provide valuable insights into the potential therapeutic targeting of these proteins." (PMID 37648771, 2023). "The molecular mechanisms and signaling pathways that may be associated with CD276 were then investigated by employing GSEA of cancers from TCGA cohort." (PMID 36717836, 2023). "Here, we demonstrate that high mTORC1 activity together with CD276 expression is associated with poor overall survival and immunosuppressive phenotypes in The Cancer Genome Atlas (TCGA) pan-cancer cohort (over 10,000 patients, across 34 different cancer subtypes)." (PMID 36869048, 2023).
cancer (continued). "In order to analyze the molecular mechanism of CD276 expression in tumorigenesis from the perspective of bioinformatics, and to investigate whether it has a connection with immune-associated signaling pathways, GSEA analysis of CD276 in cancer was performed." (PMID 36717836, 2023). "Generally speaking, CD276 may inhibit T cell infiltration, which may account for its role as a risk element in most types of cancer." (PMID 36717836, 2023). "Moreover, CD276 is a key molecule causing HNSC cancer stem cells to evade immune surveillance and is closely related to the CD8+T cell-dependent elimination of cancer stem cells." (PMID 38235126, 2023). "Overall, these findings indicated that high CD276 expression is a risk element for patients with cancer, and may predict poor survival and prognosis." (PMID 36717836, 2023). "Recent studies have shown that a new member of the B7 family (CD276, B7-H3) is overexpressed in a variety of cancer cells and is associated with disease progression, suggesting that it may serve as a potential new target for antitumor therapy." (PMID 35892678, 2022). "CD276 expression was associated positively with SRSF9 expression in most cancer types." (PMID 35069733, 2022). "However, knowledge of the cellular distribution of CD276 in cancer cells is of interest as a recent study provided evidence that cytoplasmic expression of CD276 was associated with shorter disease-specific survival of cancer patients." (PMID 35563359, 2022). "This provided a hypothesis that the high-risk OV cancers highly expressed CD276 to enhance glycolysis, which directly stimulated the amino acid metabolism of fibroblast or acidated the microenvironment to prompt fibroblast metabolism." (PMID 35783506, 2022). "The CD276 gene was significantly associated with survival in pan-cancer analysis." (PMID 35690832, 2022). "Interestingly, CD276 was positively associated with FOXM1 expression in most cancers, with the exception of CESC, CHOL, COAD, GBM, READ, SARC and UCS." (PMID 36435510, 2022). "Interestingly, we identified CD276 with an exceptionally high association with JMJD8 in 15 cancer types." (PMID 35898493, 2022). "B7-H3 (also known as CD276) is associated with aggressive characteristics in various cancers." (PMID 34552155, 2021). "In addition, the expression of CD276 was found to be positively associated with macrophages and neutrophils in TCGA pan-cancer, which suggested that CD276 may be associated with macrophage polarization." (PMID 36717836, 2023). "Notably, CD276 expression was remarkably associated with SLC6A8 in 11 of 32 types of cancer." (PMID 36061183, 2022). "Notably, in 20 of 33 types of cancer, CD276 expression was remarkably associated with TCOF1." (PMID 35093935, 2022). "Wnt, TGF‐β, and Hedgehog signaling, which are recognized as stemness‐related pathways, showed a significant association with the expression of CD200 and CD276, suggesting cancer stem cell–specific immune checkpoints could be downregulated by inhibiting these pathways." (PMID 33932112, 2021). "CD276 (B7-H3), a B7 family immune checkpoint molecule, is overexpressed in many cancers including CRC." (PMID 41710281, 2026). "B7-H3 (CD276), a member of the B7 family of proteins, is known to play a key role in the progression of a number of cancers." (PMID 41677606, 2026). "CD276, on the other hand, displayed relatively high, uniform expression in both NENs and ADCs across all six sites, corroborating its potential as a pan-cancer target." (PMID 39874041, 2025). "Currently, CD276-targeted monoclonal antibodies and antibody-drug conjugates are undergoing clinical trials as promising cancer immunotherapies." (PMID 40936932, 2025). "CD276 is reportedly overexpressed in many different cancer entities, but can also be present in healthy tissues." (PMID 40469103, 2025). "Recently, B7H3/CD276 gained much interest in cancer immunotherapy due to its significantly higher expression in tumors." (PMID 40805163, 2025).
cancer (continued). "CD276 (also known as B7-H3) is an immune-checkpoint with several additional pro-tumorigenic properties, such as increased migration or chemoresistance of cancer cells." (PMID 40469103, 2025). "Further elucidation of CD276’s functional roles is warranted to fully understand its implications in cancer biology and immunotherapy." (PMID 39994264, 2025). "ENHO also demonstrated negative correlations with immune checkpoint molecules CD276 (B7-H3) and CD70, both of which are associated with immune suppression and adverse outcomes in cancer." (PMID 40647442, 2025). "The performance of the AMs was tested in additional CD276-positive cell lines from various cancer entities, confirming the high efficacy of AM46." (PMID 40722088, 2025). "The immune checkpoint protein B7-H3 (CD276) is overexpressed in various cancers and is an attractive target for the treatment of malignant tumors." (PMID 40109742, 2025). "We found that cancer-cell-derived blebbisomes express not only PD-L1 but also a plethora of other inhibitory ligands, including PD-L2, B7-H3 (CD276), VISTA (B7-H5), HLA-E, PVR (CD155) and Nectin-2 (CD112)." (PMID 39984653, 2025). "Fucosyltransferase 8 (FUT8) is highly expressed in cancer cells, which is responsible for mediating the core fucosylation of the key immune checkpoint molecule, CD276 (B7-H3)." (PMID 40083922, 2025). "The B7 homolog 3 (CD276) is a transmembrane molecule expressed in several types of cancers where it functions as an immune checkpoint receptor, and it can be targeted efficiently by both CAR-T cells and mAb." (PMID 40677711, 2025). "CD276, a member of the B7 family, has been identified as a potential target for cancer immunotherapy due to its role in promoting cancer cell aggressiveness and facilitating angiogenesis within tumors." (PMID 39858080, 2025). "Although CD276 and hnRNPM have roles in immune modulation and cancer, their observed patterns in individuals infected with Schistosoma haematobium in our study indicate a potentially specific involvement in this infection." (PMID 40853910, 2025). "In breast cancer, the colocalization of CD276 and CD147 within lipid rafts has been implicated in the maintenance of cancer stem cell properties." (PMID 41479915, 2025). "To confirm previously shown CD276 specificity, we screened other cancer cell lines for their CD276 expression." (PMID 40469103, 2025). "CD276 plays a role in enhancing cancer cell survival by inhibiting natural killer-induced cell lysis." (PMID 38664641, 2024). "Recent mounting evidence have proved that CD276 is expressed in a variety of solid cancer cells and is an excellent pan-cancer target." (PMID 38978106, 2024). "B7-H3 (CD276) belongs to the B7 superfamily of molecules and shows potential as a promising target for cancer treatment." (PMID 38468228, 2024). "When investigating the relationship between immune checkpoint expression and PSME3, we observed that among the 33 cancers, CD276 and CD274 exhibited the highest positive correlation with PSME3, followed by VEGFA, HMGB1, THR4, BTNA2, and ENTDD1." (PMID 38312840, 2024). "Most selected genes were positively correlated with CD8+ T cells in all cancer types, except for CD276, which was negatively correlated with CD8+ T cells." (PMID 39911580, 2024). "The incidence of cancer was also lower in CD276 wKO mice than in WT mice at 16, 20, 24 and 26 weeks." (PMID 38561369, 2024). "This suggests that the immunosuppressive environment influenced by CD276 helps cancer cells evade destruction by immune cells." (PMID 38637557, 2024). "The potential relationship between RAB3B and CD276 can act as a unique potential target for cancer immunotherapy." (PMID 38688977, 2024). "Studies have shown that CD276, as an immune checkpoint, enables cancer stem cells to evade immune surveillance." (PMID 38688977, 2024). "Recently, the B7 homolog three protein (B7-H3, also known as CD276) has emerged as a significant immunoregulatory target for cancer." (PMID 38694508, 2024).
cancer (continued). "CD276, also known as B7-H3, serves as a key immune checkpoint molecule which is highly expressed in malignant tumours." (PMID 38398141, 2024). "The type I transmembrane protein B7-H3 (CD276) is overexpressed on a variety of cancers making it a promising target for antibody-based immunotherapeutic approaches." (PMID 38322253, 2024). "Recently, CD276 had been found to be overexpressed in various cancers, including breast, non‐small cell lung, and ovarian cancer, suggesting its potential as a promising immunotherapeutic target." (PMID 39210603, 2024). "Currently, the potential therapeutic effect of inhibiting CD276 on cancers has attracted people’s attention." (PMID 39766794, 2024). "B7‐H3 (CD276) is highly expressed in different types of human cancers, and there are a number of clinical trials on anti‐CD276 antibodies for hematologic and solid tumor malignancies." (PMID 40625454, 2024). "Significant upregulation was observed for the mRNA expression of B7-H3 (CD276), a member of the B7 family that plays an immunoregulatory role in the T-cell response, highlighting this molecule as a novel potential target for cancer immunotherapy." (PMID 38539537, 2024). "CD276 was also negatively correlated with activated NK cells, but positively correlated with M2 macrophages in most cancer types." (PMID 39911580, 2024). "Among these coexpressed immunostimulators, the role of highly expressed CD276 (B7-H3) as an immune checkpoint target in cancer cells is inhibition of T-cell function and CD8+ T-cell infiltration." (PMID 38655053, 2024). "B7‐H3 (CD276), an immune checkpoint overexpressed in various cancers, including urothelial‐cell carcinoma (UCC), has been associated with chemoresistance and poor oncologic outcomes." (PMID 39539559, 2024). "PSME3 emerges as a key factor positively regulating the immune checkpoint CD276 in various cancers, including LIHC, LUAD, and BLCA." (PMID 38312840, 2024). "Our study revealed a strong connection between CDCA5 and the immune gene CD276 in various cancer types." (PMID 38213717, 2024). "A recent study has demonstrated the significant involvement of CD276 in the proliferation, invasion, and migration processes of cancer cells." (PMID 38778403, 2024). "Recent reports elucidated that B7-H3 (B7 homolog 3 protein, also known as CD276) controlled cancer progression and prolonged the survival of patients via targeted chimeric antigen receptor (CAR)-T cells and CAR-NK cells." (PMID 38172945, 2024). "Pan-cancer analysis based on GEPIA also revealed high expression of CD276 in 15 types of malignancies." (PMID 38182561, 2024). "The transmembrane protein CD276 (B7-H3), a member of the immunomodulatory B7 family, recently receives great interest as target for cancer immunotherapy." (PMID 39367484, 2024). "There is evidence indicating that CD276 exhibits high expression in cancer cells as well as in activated immune cells infiltrating tumors." (PMID 39507618, 2024). "The cBioPortal database was then utilized to explore the categories and frequencies of genetic alterations of CD276 for different types of cancer." (PMID 36717836, 2023). "ANXA2 expression was variably related to the immune checkpoints in all 33 types of cancer, with the most relevant correlation being with CD276 (31/33)." (PMID 36713082, 2023). "B7 homolog 3 protein (B7-H3), also known as CD276 (B7-H3/CD276), is a promising therapeutic target for anti-cancer treatment." (PMID 37848956, 2023). "TCGA and GTEx datasets were then employed to evaluate the differences in CD276 mRNA expression comparing between different types of cancer and normal tissues." (PMID 36717836, 2023). "B7H3 (CD276) is a newly found immune checkpoint of the B7 family, representing a good target for cancer immunotherapy." (PMID 37370746, 2023).
cancer (continued). "A comprehensive evaluation of CD276 expression and prognosis in 33 types of cancer showed that CD276 expression levels were dysregulated in most types of cancer, a finding that was in line with a previous study." (PMID 36717836, 2023). "CD276 (B7-H3) is a member of the B7 immune checkpoint family and is thought to promote an immunosuppressive response as it is highly expressed in many cancers that correlate with poor clinical outcomes." (PMID 37749142, 2023). "To meet proportional hazards, we selected the 11 cancer types with death events greater than 20 from patients with high and low mTORC1 score and high and low CD276 expression." (PMID 36869048, 2023). "CD276, an immune checkpoint molecule, regulates cell proliferation, invasion, and migration of malignant tumors." (PMID 37540295, 2023). "Together, high mTORC1 score, high CD276 expression, or both with the aggregated patterns across cancer types." (PMID 36869048, 2023). "CD276 contributes to avoiding cancer cells from immune destruction by shaping the suppressive immune microenvironment." (PMID 37974070, 2023). "By comparing CD276-positive cancer cell lines with CRISPR-Cas9-engineered isogenic CD276-KO controls, we verified that target expression is essential for potent (subnanomolar) activity of the m276-SL-PBD ADC, but not for the PBD-free drug SGD1882." (PMID 38019654, 2023). "Cancer stem cells (CSCs) evade immune surveillance by utilizing CD276 in the malignant progression of neck squamous cell carcinoma." (PMID 37974070, 2023). "The association between CD147 and CD276 expression and adverse clinical outcomes in TNBC patients provides insights into the potential role of these markers in cancer stemness and drug resistance." (PMID 37648771, 2023). "An unexpected discovery that emerged while testing the sensitivity of a panel of cancer cell lines, all with similar CD276 levels, was that cancer sensitivity to m276-SL-PBD depended not only on the presence of target, but also on the cancer type." (PMID 38019654, 2023). "Taken together, these results suggested that CD276, as an immunosuppressor gene, is hypomethylated in the majority of cancer types." (PMID 36717836, 2023). "Overexpressed CD276 has been reported in numerous malignant tumors, which were reported to advance the metastasis of cancer cells." (PMID 37514090, 2023). "In the present study, we also investigated the pathological and clinical significance of CD276 in different types of cancers in TCGA, and CD276 expression at the different cancer stages." (PMID 36717836, 2023). "Previous studies find the correlation between PDIA3 and NRP1, CD276 was also very significant in pan-cancer." (PMID 37251370, 2023). "Subsequently, the monocellular immune module from the TIGER database was used to analyze CD276 expression in various types of cancer and their corresponding immune cells." (PMID 36717836, 2023). "While testing m276-SL-PBD against 57 CD276-positive cell lines, all exhibiting similarly high levels of CD276, it became evident that the sensitivity of each cell line was also highly dependent on the cancer cell type." (PMID 38019654, 2023). "Our study found that CD276 was mainly found in the intracellular membrane of patients with cancer, although it was also highly expressed in the vesicles of the A-431, U-2 OS, and U251 MG cell lines." (PMID 36717836, 2023). "Taken together, our data provide compelling evidence for the lateral interaction between CD147 and CD276, sequestered within LRMs, as a crucial determinant of the drug resistance phenotype in cancer stem cells (CSCs) and the pathological features of human BC." (PMID 37648771, 2023). "A previous study showed that CD276 is able to induce antigen-presenting cells and has a crucial role in inhibiting T-cell function, suggesting that it is a promising target for cancer immunotherapy." (PMID 36717836, 2023).